CDH1 (cadherin 1)
Diseases named in the same sentence as CDH1 in open-access papers (continued):
Sharing a sentence is not in itself a finding about the gene and the disease.
gastric cancer (continued). "The distinction between hereditary diffuse gastric cancer (HDGC) and hereditary lobular breast cancer (HLBC) made by the International Gastric Cancer Linkage Consortium (IGCLC) in 2020 acknowledges the likelihood that not all families with pathogenic CDH1 variants are equally at risk of DGC." (PMID 37761816, 2023). "If there is no family history of gastric cancer, carriers of a PV in CDH1 or CTNNA1 may consider either risk-reducing total gastrectomy or yearly surveillance." (PMID 37165697, 2023). "Repeated observation of the cohort of gastric cancer patients without CDH1 mutations discovered CTNNA1 mutations (2/28), supporting the hypothesis that pathogenic CTNNA1 variants are the rare causes of gastric cancer." (PMID 36741258, 2023). "Indeed, whole-exome sequencing studies conducted on families with hereditary gastric cancer but lacking pathogenic mutations in the CDH1 gene, which encodes E-Cadherin, have identified two RECQ5 variants, namely c.2828C>T and c.2806-2A>G, in separate families." (PMID 37626846, 2023). "For CDH1 carriers, early estimates of DGC risk were as high as 83 per cent by 80 years of age132; however, more recent data, ascertained with less bias toward gastric cancer predominant families, have shown gastric cancer risks of 33–42 per cent by 80 years of age110,111." (PMID 37165697, 2023). "Somatic mutations CDH1 and copy number gains of FGFR2 were identified to enrich in the younger gastric cancer patients, which may contribute to the worse prognosis of early-onset gastric cancer patients." (PMID 35498538, 2022). "If CDH1 mutation is detected without the phenotypical manifestation of gastric cancer, it is an ongoing debate whether to recommend surgical resection or endoscopic control." (PMID 35887173, 2022). "Combined with genome-wide siRNA screening in CDH1+/+ and CDH1−/− cells, and analysis of expression patterns correlated with CDH1 levels in TCGA gastric cancer datasets, we predicted that this might reflect wider perturbations to membrane organization and vesicle trafficking." (PMID 35008266, 2021). "For example, specifically in the context of CDH1 mutation carriers, most asymptomatic individuals do not have macroscopic lesions on endoscopic examinations; however, intramucosal foci of gastric cancer, usually multiple, are observed in the surgical specimens." (PMID 34201547, 2021). "Major syndromes associated with GC are hereditary diffuse gastric cancer (HDGC; mutations in CDH1), gastric adenocarcinoma, proximal polyposis of the stomach (GAPPS; YYP1 binding motif of APC) and familial intestinal gastric cancer (FIGC)." (PMID 34576114, 2021). "Prophylactic gastrectomy in carriers of CDH1 pathogenic variants without a personal/family history of gastric cancer may not be appropriate, given the significant morbidity associated with this intervention." (PMID 34771713, 2021). "More aggressive interventions may be recommended, such as consideration of prophylactic gastrectomy if a CDH1 mutation is found, even in the absence of gastric cancer in the family." (PMID 33959510, 2021). "On the other hand, unbiased screening may lead to an over selection of individuals harboring CDH1 variants that, certainly, do not award increased risk of developing gastric cancer." (PMID 33809393, 2021). "Diffuse gastric cancer with CDH1 mutation has more aggressive phenotypic characteristics, and targeted E-cadherin therapy may provide new ideas for inhibiting tumor metastasis, which can be used as a potential target for future gene and genetic therapy and has important value." (PMID 34422902, 2021).
gastric cancer (continued). "However, the frequency of CDH1 germline mutation in unselected gastric cancer cases is not well established." (PMID 31892987, 2020). "In addition to CDH1 mutations, mutations in many other genes involved in homologous recombination such as BRCA1, BRCA2, PALB2 and others, were also reported to increase the risk of gastric cancer 12-14." (PMID 32373223, 2020). "Hereditary diffuse gastric cancer syndrome (HDGC) is the most common inherited entity related to GC, involving a germline mutation in CDH1 and much less frequently in CTNNA1, with a cumulative risk of GC of up to 80%." (PMID 32842532, 2020). "The aim of this study was to characterize CDH1 mutations associated with HDGC from Chile, a country with one of the highest incidence and mortality rates in the world for gastric cancer (GC)." (PMID 31600923, 2019). "However, since the majority of these cases were diagnosed as a result of prior familial HDGC screening, these figures do not accurately represent the prevalence of pathogenic CDH1 mutations in the Māori gastric cancer population." (PMID 29589180, 2019). "Additionally, we estimate that in absence of screening, 6% of all advanced gastric cancer and 13% of all advanced diffuse-type gastric cancers in the Māori population would carry germline CDH1 mutations." (PMID 29589180, 2019). "Patients with metastatic HDGC typically receive the same, largely ineffective chemotherapies as patients with sporadic gastric cancer; however, HDGC patients experience inferior outcomes to sporadic gastric cancer or gastric cancer with non-pathogenic CDH1 mutations." (PMID 29468433, 2018). "Carriers can develop advanced gastric carcinoma as early as age 14 years or may never develop cancer owing to incomplete penetrance, which occurs in 20–30% of CDH1 germline mutation carriers." (PMID 30568591, 2018). "Although MSI-H gastric cancers are hyper-mutated, MSS gastric cancers also possess a high frequency of genetic alterations such as CDH1, RHOA, HER2, EGFR, VEGFR, MET, and FGFR2, all of which may directly or indirectly affect the MAPK and PI3K/Akt survival pathways." (PMID 29137273, 2017). "There is strong evidence showing a positive association between the mislocalized, diminished or absent E-cadherin immunoreactivity and gastric cancer, and therefore, whenever possible, it is important to define the pathogenicity, as well as phenotypic manifestations, of CDH1 variants." (PMID 24838934, 2014). "However, findings related to the influence of the −160C → A promoter polymorphism and haplotypes of the E-cadherin (CDH1) gene have not been consistent in previous studies regarding the risk for sporadic gastric cancer." (PMID 24684952, 2014). "These advanced gastric carcinomas of CDH1 mutation carriers do not show any characteristics that might discriminate them from sporadic gastric cancers." (PMID 23231819, 2012). "However, no mono-allelic hypermethylation of the CDH1 promoter was found in any of the samples, suggesting that it is not a predisposing factor for gastric cancer." (PMID 19671196, 2009). "Notably, the CDH1 gene, historically responsible for hereditary diffuse gastric cancer, has recently emerged as associated with lobular BCs, even in the absence of a personal or family history of gastric cancer." (PMID 40361347, 2025). "Individuals with CDH1 P/LP variants may assume their individual cancer risk mirrors that of affected family members; however, our results do not support a familial pattern of age of onset of advanced gastric cancer." (PMID 39760880, 2025). "Interestingly, many women with HLBC have a family history of gastric cancer, though they may not develop gastric cancer themselves, underscoring a dual but variable cancer risk associated with CDH1 mutations." (PMID 40366456, 2025).
gastric cancer (continued). "With regard to gastric cancer, most cases in our cohort were observed in families carrying PVs in BRCA2 and CDH1." (PMID 40649708, 2025). "Cdh1 dysregulation is implicated in gastric tumorigenesis as well as in tumor progression, invasion, and metastasis and serves as a negative prognostic factor for gastric cancer, which is essentially integrated in the molecular classification of gastric cancer." (PMID 39000189, 2024). "Of different types of gastric cancer only hereditary diffuse gastric cancer (HDGC) is known to be inherited and is associated with the presence in approximately 45% of familial cases with a mutation in the E-cadherin gene (CDH1), but the genetic background of other cases remains unknown." (PMID 38867324, 2024). "Of the three CDH1 repressors SNAIL, SLUG, and TWIST, YWHAH robustly interacted with SLUG in gastric cancer cells, which was inhibited by silencing AKR1B1 and/or SORD." (PMID 38200154, 2024). "However, this technique may be more appropriate for patients undergoing prophylactic gastrectomy due to CDH1 gene mutations, which are associated with gastric cancer, rather than for those with non-genetic HGM of the GB." (PMID 39588436, 2024). "Some 10% of subjects with GC have a positive family history and > 3% are related to hereditary syndromes, the most common one being hereditary diffuse gastric cancer (HDGC) syndrome, caused by cadherin 1 gene (CDH1) alterations." (PMID 39023829, 2024). "Since invasive diffuse type GC is associated with a high mortality, the International Gastric Cancer Linkage Consortium (IGCLC) guidelines recommend prophylactic total gastrectomy (PTG) for carriers of pathogenic CDH1 germline mutations." (PMID 35499650, 2023). "We unveiled a mechanism explaining the E- to P-cadherin switch (CDH1 to CDH3 switch), which we found to occur in many gastric cancers." (PMID 37372088, 2023). "Germline genetic testing of CDH1 and, recently, CTNNA1 is recommended when an individual fulfills the clinical criteria according to the updated guidelines of the International Gastric Cancer Linkage Consortium (IGCLC)." (PMID 37239438, 2023). "The suppression of STK24 increased cell migration by inhibiting CDH1 (E-Cadherin) and enhancing the levels of CD44 in gastric cancer cells." (PMID 37202821, 2023). "Only two HDGC families have been reported to carry large deletions involving specifically CDH1 and TANGO6, both presenting early-onset DGC and gastric cancer in consecutive generations." (PMID 37249750, 2023). "CDH1 mutation is also the major germ line genetic deficiency in the hereditary diffuse gastric cancer [HDGC], an autosomal dominant syndrome characterized by the onset of GC in young patients." (PMID 36556227, 2022). "Previous research in our laboratory demonstrated that CDH1-null cells have increased sensitivity to allosteric AKT inhibitors (ARQ-092, MK2206) compared to CDH1-expressing cells (in isogenic mammary and gastric cancer cell line pairs)." (PMID 35406381, 2022).
gastric cancer (continued). "We used the human gastric cancer line AGS, which lacks E-Cadherin (CDH1) and in this regard, models diffuse type gastric adenocarcinoma, which has a strong predilection for peritoneal spread." (PMID 35798764, 2022). "Based on the International Gastric Cancer Linkage Consortium (IGCLC), this case meets the third criterion for CDH1 germline screening." (PMID 36011265, 2022). "We also identify CDH1 as a potential negative regulator of AKAP9 expression, through which CDH1 regulates gastric cancer migration and invasion." (PMID 36317124, 2022). "Actually, the genes CDKN2A, CDH1, and RUNX3 found in gastric cancer and in precancerous lesions of Hp-infected patients inactivate the tumor-suppressor genes." (PMID 35163679, 2022). "In order to clarify the role of EMT and distant metastasis, we first analyzed the mRNA expression of VIM, CDH1, S100A4 and EPCAM in human gastric cancer samples from the Cancer Genome Atlas (TCGA) data." (PMID 33535187, 2021). "In the context of EMT, TGF-b1 treatment in gastric cancer cells promotes the expression of JARID1A demethylase, which is recruited by p-SMAD3 to CDH1 promoter, leading to gene silencing and promoting malignancy." (PMID 34901003, 2021). "By analyzing the DNA methylation data of TCGA gastric cancer database, there were 12 DNA methylation sites in VIM, 8 in CDH1, 3 in S100A4, 7 in EPCAM, and 6 in VCL." (PMID 33535187, 2021). "Neutrophils in the stroma of gastric cancer (GC) produce IL17a and CXCL5 both promoting EMT, indicated by upregulation of VIM and ZEB1, whereas CDH1 is repressed." (PMID 34459003, 2021). "In NCI-N87 cells, a gastric cancer cell line with a highly dysregulated genome, synthetic lethality between SPHK1 and CDH1 was abrogated, demonstrating the importance of genetic background to SPHK1′s synthetic lethality." (PMID 35008266, 2021). "In gastric cancer family 3, the maternal grandmother (I.2) of patient III.1, who carried a heterozygous deletion of CDH1 exons 1 to 2 and was affected by gastric cancer, suffered from a brain tumor, NOS." (PMID 33929593, 2021). "It is also described as a master regulator of the EMT by overexpressing Snail, Slug, and vimentin and suppresses E-cadherin (CDH1) expression in endometrial cancer and gastric cancer, but less has been explored in the HER2+ BC subtype." (PMID 33014831, 2020). "In 1999, the International Gastric Cancer Linkage Consortium (IGCLC), defined specific clinical criteria to select individuals for CDH1 genetic screening and introduced the definition of a new syndrome, the so-called Hereditary Diffuse Gastric Cancer (HDGC)." (PMID 32560361, 2020). "In this study weperformed Next Generation Sequencing (NGS) to assess CDH1 germlinemutations in individuals who match the clinical criteria for Hereditary DiffuseGastric Cancer (HDGC), or who exhibit very early diagnosis of gastric cancer." (PMID 27192129, 2016). "We found a decreased expression of the epithelial markers CDH1, EpCAM, and increased expression of the mesenchymal markers CDH2, Vimentin, ZEB1, Snail, MMP14 and Twist in un-captured cells in gastric cancer cell lines AGS, SGC7901 and BGC-823." (PMID 27654478, 2016). "We previously showed that the intestinal-type with epithelial characteristics and the diffuse-type with mesenchymal characteristics can be clearly distinguished using the ratio of CDH1 (E-cadherin) mRNA and CDH2 (N-cadherin) mRNA in gastric cancer." (PMID 26625258, 2015).
gastric cancer (continued). "In gastric cancer, a large number of genes (e.g., CDKN2A, CDK2AP2, CDH1, MGMT, RASSF1, RUNX3, and DLC1) have been shown to be suppressed by CpG island hypermethylation." (PMID 23179365, 2013). "CDH1 methylation was detected by real-time methylation specific-PCR in tumor tissues and corresponding PPW from 92 gastric cancer patients, gastric mucosa from 40 chronic gastritis patients and 48 normal persons." (PMID 22514028, 2012). "The percentage of CDH1 methylation in PPW was 48.9%, of which the Aζ value of ROC curve was 0.8 compared to that in gastric cancer tissues." (PMID 22514028, 2012). "Prior studies have shown loss of three critical tumor suppressor gene products, CDH1 (E-cadherin), p73, and CDKN2A (p16), in EBV-infected gastric cancers." (PMID 21194482, 2010). "Since all of the patients with familial gastric cancer or early-onset gastric cancer whose samples we analyzed had already been shown to be negative for germline CDH1 mutation, genetic or epigenetic events in other genes may have been involved in the gastric carcinogenesis in those patients." (PMID 19671196, 2009). "CDH1 and CTNNA1 remain as the main genes for hereditary gastric cancer." (PMID 38796558, 2024). "For c.1320+1G>A in the CDH1 gene and c.G1874C in the FANCA gene we used DNA samples isolated from the peripheral blood of 200 patients with gastric cancer and 200 healthy donors, as well as 70 DNA samples from the tumor tissue of the stomach of patients with cancer." (PMID 36833207, 2023). "Herein, we aimed to characterize a potential 3D chromatin architecture re-wiring process, occurring at the CDH3–CDH1 loci, that may explain the CDH1/E-cadherin to CDH3/P-cadherin switch observed in gastric cancer." (PMID 37372088, 2023). "We have previously shown that AKT3, but not AKT1 or AKT2, is upregulated in gastric cancers with low CDH1 expression and have identified an E-cadherin-AKT synthetic lethal relationship." (PMID 35406381, 2022). "For example, the CDKN2A, CDH1 and RUNX3 genes found in precancerous lesions of H. pylori-infected patients and gastric cancer patients could inactivate tumor suppressor genes." (PMID 36310856, 2022). "We have previously identified AKT3 as a potential vulnerability in gastric cancers lacking CDH1 expression." (PMID 35406381, 2022). "In multiple gastric cancer datasets, TGFβ were positively correlated with EMT score and mesenchymal markers (CDH2, VIM and ZEB1), while significantly negatively correlated with epithelial marker CDH1." (PMID 36119489, 2022). "Furthermore, in the context of EMT, TGF-β1 treatment in gastric cancer cells induced expression of JARID1A demethylase, which is recruited by p-SMAD3 to CDH1 promoter, inducing its silencing, and promoting malignant progression." (PMID 33803458, 2021). "We determined the DNMT3A genotype and CpG methylation status of 4 genes (p14ARF, p16INK4a, DAPK, and CDH1) in 510 subjects without gastric cancer." (PMID 33066747, 2020). "Moreover, E-cadherin, which is coded by CDH1 gene, regulates signaling pathways leads to increase in cell proliferation, decrease in cell apoptosis followed by gastric cancer development." (PMID 32727394, 2020). "While no pathogenic somatic mutations were found that could explain the diffuse histology of gastric cancer in DGC and MGC, methylation was the most common somatic inactivation event of the CDH1 gene, and LOH was rare." (PMID 30642281, 2019). "Although this is a possibility, it has not yet been demonstrated that the expression of a CDH1 aberrant transcript in gastric cancers is controlled by H. pylori." (PMID 31781079, 2019). "The studies have shown that genetic alterations in the RhoA pathway, including recurrent RHOA mutations and RhoGAP fusion along with the CDH1 mutations, are quite common in DGC but not in other variants of gastric cancer." (PMID 30115886, 2018).